BRCA2 (BRCA2 DNA repair associated)
Diseases named in the same sentence as BRCA2 in open-access papers (continued):
Sharing a sentence is not in itself a finding about the gene and the disease.
breast cancer (continued). "The lifetime risk for breast cancer in a male BRCA2 mutation carrier is 7%, 80-100 times higher than for the general population." (PMID 29697934, 2018). "It was noted that two individuals with breast cancer with germline BRCA2 mutation also carried another deleterious germline mutation, respectively." (PMID 29464067, 2018). "Of 115 BRCA2 mutation carriers, 98 subjects had breast cancer (78 single cases, 18 cases with 2 breast cancers, 2 with 3 breast cancers)." (PMID 29176636, 2018). "This is, for example, the case for tumours with high levels of genomic instability, such as Brca1/Brca2-deficient breast cancer models." (PMID 30111589, 2018). "Together, BRCA1 and BRCA2 mutations account for about 20–25% of hereditary breast cancers and about 5–10% of all breast cancers." (PMID 29445722, 2018). "BRCA2, a tumor suppressor that is essential for the repair of double-strand DNA breaks by homologous recombination, is associated with risk of developing breast cancer." (PMID 30370249, 2018). "Loss of function PALB2 pathogenic variants confer a breast cancer risk of 35% by age of 70, that is comparable to that conferred by BRCA2 pathogenic variants." (PMID 30410870, 2018). "Women carriers of BRCA1 or BRCA2 mutation seem to have a potential risk of 72% and 69% to develop breast cancer and a risk of 44% and 17% to develop ovarian cancer respectively." (PMID 30340058, 2018). "In other words, risks of breast cancer to BRCA1 or BRCA2 mutation carriers is context dependent and varies by geography and the social environment in which the mutation carrier lives." (PMID 30130155, 2018). "Previous studies have demonstrated that a single nucleotide polymorphism (SNP) in FBXL7 showed the strongest associations in BRCA2 mutation carriers of breast cancer." (PMID 30301218, 2018). "This is the first study to investigate the association of selected genetic polymorphisms in breast cancer related genes (apart from BRCA1 and BRCA2) and the susceptibility to sporadic breast cancer in the Sri Lankan population." (PMID 29433565, 2018). "Women who inherit a deleterious BRCA1 or BRCA2 mutation face substantially increased risks of developing breast cancer, which is estimated at 70%." (PMID 30572612, 2018). "Germ-line mutations in BRCA1 and BRCA2 genes are associated with ~60–90% probability of developing breast cancer and 40–60% life-time risk of ovarian carcinoma." (PMID 30211169, 2018). "BRCA2 mutations are responsible for up to 1% of unselected UK prostate cancer cases and for only up to 0.2% of unselected Polish breast cancer cases." (PMID 30286154, 2018). "Examination of the role of BRCA1 and BRCA2 in the DNA damage response has led to the identification of several breast cancer susceptibility genes such as FALB2, CHEK2, BRIP1, all of which interact directly or indirectly with BRCA1 or BRCA2." (PMID 30249004, 2018). "Deleterious variants of the most prevalent genes BRCA1 (MIM# 113705) and BRCA2 (MIM# 600185) confer up to 87% of risk to develop breast cancer by the age of 70 years." (PMID 29881398, 2018). "For a patient with breast cancer that is caused by an inherited heterozygous BRCA2 mutation, only the tumor cells are mutant for BRCA2 due to LOH." (PMID 31435521, 2018). "For example, if the parents receive findings regarding breast cancer because of mutations in BRCA1 or BRCA2 genes, it can conflict with the child’s right to an open future if knowledge is disclosed that the child would have wanted to live without as an adult." (PMID 29506557, 2018). "BRCA2 is the predominant gene mutated in breast cancer patients in this population, with a single mutation, E1308X accounting for 88% of the alleles." (PMID 30400234, 2018). "The primary aim of this study was to determine the effect of a germline BRCA1 or BRCA2 mutation on breast cancer outcomes in patients with young-onset breast cancer." (PMID 29337092, 2018).
breast cancer (continued). "Identifying female carriers of BRCA1 and BRCA2 mutations is imperative for prevention of ovarian cancer and breast cancer." (PMID 29506471, 2018). "Mutations in two prominent susceptibility genes, BRCA1 and BRCA2, were identified as major risk factors for breast cancer." (PMID 30249004, 2018). "If an individual has a family history of breast cancer or has inherited genetic mutations, such as BRCA1 and BRCA2, she is at a significantly higher risk of developing breast cancer." (PMID 29713580, 2018). "We have characterized the BRCA1 and BRCA2 variants in 307 unselected breast cancer patients in Puerto Rico." (PMID 30400234, 2018). "Eligible patients for this study were healthy women with ≥ 17% lifetime risk of breast cancer or with a mutation in BRCA1 or BRCA2." (PMID 29318406, 2018). "Previously published case reports have shown that carriers of BRCA1 and BRCA2 mutations formed angiosarcomas following radiation treatment of breast cancer." (PMID 29515789, 2018). "We will also conduct a meta-analysis to integrate available estimates of breast cancer risk in Asian women carrying a BRCA1 or BRCA2 germline mutation into a consensus estimate of penetrance." (PMID 29861850, 2018). "They reported that a later age at first birth was the only probable risk factor for BRCA1-associated breast cancer, with less evidence for the role of reproductive factors for women with a BRCA2 mutation." (PMID 30572612, 2018). "Additional germline variants in several other genes, including PALB2 (partner and localizer of BRCA2) (MIM#610355) have also been implicated in increased predisposition to breast cancer." (PMID 30410870, 2018). "The frequencies of BRCA mutations were 10.5% from a cohort of 409 Chinese breast cancer patients in Northern China, and BRCA2 mutations were more common than BRCA1." (PMID 29487695, 2018). "A wide range of histological subtypes, mainly a luminal hormone receptor positive phenotype, can be seen in breast cancer patients with BRCA2 germline mutation." (PMID 29453630, 2018). "While displaying similar roles in HR, BRCA1- and BRCA2-associated breast cancer have very different pathology and biology." (PMID 30544963, 2018). "The cancer risk for BRCA2 pathogenic variant carriers is 55% for breast cancer, 16.5% for ovarian cancer, and 62% for contralateral breast cancer." (PMID 29707112, 2018). "The BRCA2 c.9976A>T (p.Lys3326*) variant was identified for the first time in 1996 during a mutational screening program completed on families with recurrent breast cancer in Nebraska." (PMID 29346284, 2018). "Whereas of 59 breast cancers in BRCA2 mutation carriers, 18.6% were TNBC and 64.4% were luminal type, respectively." (PMID 29176636, 2018). "A major driver of risk for breast cancer is inherited mutations of genes such as BRCA2, BRCA1 and more rarely PALB2 and CHEK2." (PMID 29392096, 2018). "In conclusions, BRCA2 mutations are infrequent among early-onset melanoma patients or MM cases with a familial aggregation with breast cancer." (PMID 30286154, 2018). "For instance, mutations in the BRCA2 gene occur in about 0.2% of women and result in about a seven-fold increase in the lifetime risk of breast cancer." (PMID 30048462, 2018). "In BRCA2 mutation carriers, the breast cancer risk within two years after delivery is 70% higher than that in nulliparous women." (PMID 30202672, 2018). "In a retrospective monocentric Dutch series, 35 BRCA1- and 13 BRCA2-associated advanced breast cancers receiving either paclitaxel or docetaxel were compared with 95 sporadic forms." (PMID 30544963, 2018). "As a tumor suppressor gene, BRCA2 mutation was reported to be associated with breast cancer and ovarian cancer development." (PMID 29891014, 2018). "In conclusion, our results indicate that combining everolimus and olaparib in BRCA2 mutated breast cancer strongly inhibits expression of key proteins involved in DNA repair and results in massive DNA damage and tumor regression in vivo." (PMID 30038706, 2018).
breast cancer (continued). "In summary, these results show that treatment by everolimus combined to olaparib results in strong tumor growth inhibition with 100% of animals showing tumor regression in a PDX of ER+ BRCA2 mutated breast cancer." (PMID 30038706, 2018). "Recent studies showed that women who carry mutations in the PALB2 gene are at similar breast cancer risks as those who carry mutations in BRCA2." (PMID 29456628, 2018). "The mutations of BRCA1 and BRCA2 in human medicine are hereditary and an indicator of a high possibility of high-grade breast cancer development." (PMID 30373614, 2018). "BRCA2 pathogenic variants localized in 5’ (5’ to c.2830) and 3’ (3’ to c.6402) regions were associated with a significant higher breast cancer risk compared with pathogenic variants within the central region." (PMID 29707112, 2018). "BRCA1 mutation-associated breast cancer is more likely to be hormone receptor negative and have a higher grade and basal-like phenotype, while BRCA2-associated breast cancer resembles sporadic breast cancer." (PMID 30174725, 2018). "We used a multi-gene panel testing to identify the germline variants in a mother-daughter pair with early-onset breast cancer, and detected one pathogenic protein-truncating variant in BRCA2." (PMID 30214756, 2018). "BRCA1 and BRCA2 are the two most commonly mutated high-penetrance genes and about 15–20% of the familial breast cancer risk is attributable to germline mutations in one of these two genes." (PMID 30116257, 2018). "A possible association between melanoma and breast cancer has been reported in some studies, which suggest an independent involvement of BRCA2 in melanoma development." (PMID 30286154, 2018). "The onset age of breast cancer in the BRCA1 or BRCA2 mutation-positive group was significantly lower than that in the BRCA mutation-negative group (40.2 years, 41.7 years, and 45.4 years, respectively)." (PMID 29176636, 2018). "In this high risk ethnic Chinese cohort, 13.5% had a germline pathogenic mutation in one of twenty breast cancer susceptibility genes, and 8.3% had a BRCA1or BRCA2 mutation." (PMID 29566657, 2018). "Mutations in BRCA1 or BRCA2 have been detected in 20% of families with a history of breast cancer in Poland." (PMID 29678143, 2018). "One of the most frequently discussed mutations in breast cancer literature is the germline mutation in BRCA1 and BRCA2 genes, which accounts for about 25% of inherited breast cancers and 10% of all breast cancers." (PMID 29713580, 2018). "For example, breast cancer cells carrying mutations of the BRCA2 gene are deficient in the HR repair pathway and are consequently particularly sensitive to chemical inhibitors of alternative DNA repair pathways." (PMID 29552282, 2018). "In case of BRCA2 mutations in breast cancer, suggestive morphological and prognostic features are even more unspecific and thus less helpful." (PMID 29453630, 2018). "Curiously, c.7802A>G was reported a family with a significant history of primary cancers (colorectal, lymphoma, and breast cancers) which carried biallelic BRCA2 mutations (c.7802A>G and c.1845_1856delCT)." (PMID 29881398, 2018). "AZD2281, a PARP inhibitor, resulted in progression free survival of approximately six months in patients with BRCA1- or BRCA2-deficient advanced breast cancer (of which 50% were triple-negative)." (PMID 29190901, 2017). "Previous studies found that RAD52 depletion in BRCA2-defective breast cancer cells is associated with spontaneous and radiation-induced chromosomal aberrations." (PMID 29145865, 2017). "For example, women with pathogenic variants in breast cancer 1 (BRCA1) and BRCA2 were reported to have a cumulative lifetime risk of developing breast cancer between 41% and 90%." (PMID 29262565, 2017). "When providing genetic counseling to women with ovarian cancer and a recently identified BRCA1/BRCA2 mutation, genetic counselors have breast cancer risk management on their agenda." (PMID 28780755, 2017).
breast cancer (continued). "Approximately 25% of hereditary breast cancer cases are associated with a strong familial history which can be explained by mutations in BRCA1 or BRCA2 and other lower penetrance genes." (PMID 29108258, 2017). "Breast cancer risk management in BRCA1/BRCA2 carriers with advanced ovarian cancer is an under-explored area of genetic counseling research." (PMID 28780755, 2017). "Mutations in BRCA1 and BRCA2 genes increase the risk of ovarian cancer by 60% and breast cancer by up to 80% in women." (PMID 28651617, 2017). "A small number of studies have indicated that breast cancer risk is lower in BRCA1/BRCA2 mutation carriers after an ovarian cancer diagnosis, compared to unaffected mutation carriers." (PMID 28780755, 2017). "On the other hand, 5 SNVs were found in BRCA1 gene and one SNV associated with breast cancer risk in BRCA2." (PMID 28787462, 2017). "BRCA1 and BRCA2 genomic insertions, deletions or single nucleotide polymorphisms are also major founder mutational events and show high-risk in many breast cancer cases." (PMID 28477017, 2017). "In conclusion, our comprehensive evaluation of BRCA1/BRCA2 in families with criteria for hereditary breast cancer found three known BRCA1/BRCA2 mutations and BRCA1 c.4647_4648dupAA as a novel pathogenic." (PMID 28944232, 2017). "Mutations in the BRCA1 and BRCA2 genes are the most common causes of hereditary breast and ovarian cancer and are associated with a lifetime risk of breast cancer of 50–85% and of ovarian cancer of 15–40%." (PMID 29292755, 2017). "The majority of mutations in BRCA1 and BRCA2 (Breast Cancer Information Core, BIC database 2017) are frameshift changes resulting in nonfunctional proteins." (PMID 28944232, 2017). "Among our French Canadian cohort, 24% of high-risk breast cancer families were found to be carriers of a deleterious BRCA1 or BRCA2 mutation." (PMID 29108258, 2017). "Mutations in BRCA1 and BRCA2 genes plays vital role in the majority of hereditary cases of breast cancer." (PMID 28235003, 2017). "BRCA2‐deficient mouse mammary tumor‐derived cell lines recapitulate the responses of human breast cancers to a variety of drugs." (PMID 28729482, 2017). "The majority of mutations in BRCA1 or BRCA2 found in Latin-American breast cancer patients are private for each population, with very few mutations shared between countries." (PMID 29088781, 2017). "Approximately 15% of TNBC harbor a germline mutation in BRCA1 or BRCA2; up to 80% of BRCA1 mutation-associated and 35% of BRCA2 mutation-associated breast cancer has the TNBC phenotype." (PMID 29108297, 2017). "Improved assessments of risk have now been defined based on mutations in BRCA1 (Breast Cancer susceptibility gene 1: 39%–65% life-time risk), and BRCA2 (Breast Cancer susceptibility gene 2: 11%–37% life-time risk)." (PMID 28406427, 2017). "Consistent with this, the ER-positive PRS and the PRS for overall breast cancer constructed from general population data exhibited stronger associations than the ER-negative PRS in BRCA2 carriers." (PMID 28376175, 2017). "Seventy Nigerian breast cancer patients with ages younger than 40 years were studied, and one BRCA2 truncating mutation 3034del4 within exon 11 has been reported." (PMID 28814288, 2017). "In the reported cross-sectional study of nurses and midwives, we examined several determinants of the methylation status in two suppressor genes, namely BRCA1 and BRCA2, whose silencing predisposes to breast cancer." (PMID 28594926, 2017). "Only 32 variants (7 BRCA1 and 25 BRCA2) were present in both cases and controls and these were analyzed for association with breast cancer risk." (PMID 28222693, 2017). "Causative variants in genes such as BRCA1 and/or BRCA2 have been shown to account for hereditary nature of certain breast cancers." (PMID 29093764, 2017).
breast cancer (continued). "In contrast, multiple breast primary cancers were only identified in BRCA2 pathogenic variant carriers in this cohort, suggesting a role for first-line BRCA1/BRCA2 testing in men with this presentation." (PMID 28008555, 2017). "There is a very low detection rate of BRCA1 and BRCA2 mutations in women with HER2 amplified breast cancers." (PMID 27796713, 2017). "In breast cancer that the heterozygous genotype of 5′ UTR -26 G > A polymorphism located in BRCA2 was found to be protective effect in cancer risk." (PMID 28924235, 2017). "Genetic risk factors, such as mutations on breast cancer susceptibility gene 1 (BRCA1) and BRCA2, only account for approximately 5–10% of all breast cancer incidences." (PMID 28698459, 2017). "The strongest evidence of association with breast cancer risk in BRCA2 mutation carriers was observed for rs6982040, located at 8q11.21 in intron 74 of the PRKDC gene (p = 2.7 × 10−3)." (PMID 27796716, 2017). "Genetic testing for breast cancer 1 (BRCA1) and breast cancer 2 (BRCA2) gene mutations can identify women at increased risk for breast and ovarian cancer." (PMID 28880857, 2017). "In Chile, we and others have carried out mutation screening of BRCA1 and BRCA2 in hereditary breast cancer patients, leading into mutation frequencies ranging from 15% to 20%." (PMID 29088781, 2017). "In the setting of breast cancer, a proof of concept study was conducted to assess the efficacy, safety, and tolerability of olaparib alone in women with BRCA1 or BRCA2 mutation advanced breast cancer." (PMID 28454587, 2017). "BRCA1 and BRCA2 are the first genes found to be associated with a higher predisposition to breast cancer." (PMID 28449691, 2017). "The 10-year breast cancer risk in women with BRCA1/BRCA2-associated ovarian cancer was 11%, compared to 28% in the control group (mortality rates at five and ten years were 33% and 61%, respectively)." (PMID 28780755, 2017). "The present study estimated the prevalence of BRCA1 and BRCA2 gene mutations in a broad Colombian population of 853 breast cancer patients." (PMID 29021639, 2017). "There appeared to be considerable discrepancies in the causative variant rates of BRCA1 and BRCA2 in breast cancer patients in different areas of China." (PMID 29093764, 2017). "Breast cancer 1 (BRCA1) and breast cancer 2 (BRCA2) are commonly used gene markers for breast cancer susceptibility." (PMID 28678153, 2017). "Inherited breast cancer is caused by penetrant susceptibility genes and most often involves germ line mutations of the BRCA1 and BRCA2 genes in about 15% of familial breast cancer patients." (PMID 28741261, 2017). "Unaffected women who carry BRCA1 or BRCA2 mutations face difficult choices about reducing their breast cancer risk." (PMID 28624978, 2017). "We identified 43 deleterious mutations in BRCA1 and BRCA2 (39 new and 4 previously reported founder mutations), all of them involved in the development of breast cancer." (PMID 29021639, 2017). "Several studies have reported an increased risk for developing breast cancer in women with either BRCA1 or BRCA2 mutations following exposure to medical radiation, either through mammography or radiation therapy." (PMID 28865460, 2017). "At the age of 80, cumulative cancer risk for BRCA1 and BRCA2 mutation carriers ranges from 72% to 69% for breast cancer development, and from 44% to 17% for ovarian cancer." (PMID 29383107, 2017). "We found that the highest risk of breast cancer was associated with the frame shift mutation BRCA2/1991del4, but this result needs validation due to the small number of women investigated in the analysis." (PMID 28680148, 2017). "Females carrying mutations in genes related to DNA repair, such as BRCA1 and BRCA2, had higher risk for breast cancer." (PMID 28813639, 2017). "Carriers of mutations in the BRCA1- or BRCA2 gene (breast cancer genes) have a substantially increased risk of both breast and ovarian cancer." (PMID 28096903, 2017).